ISG15 (ISG15 ubiquitin like modifier)
Diseases named in the same sentence as ISG15 in open-access papers (continued):
Sharing a sentence is not in itself a finding about the gene and the disease.
ZIKV infection (28 papers, 2017 to 2025). "For example, ZIKV infection of A549 cells has been associated with down-regulated expression of ISGs including ISG15, IFIT1, and IFIT2 in response to IFN-β treatment, as compared to mock infection." (PMID 31652496, 2019). "At 36 h post-ZIKV infection, the expression levels of interferon-induced antiviral proteins, including ISG15, ISG56, OAS1, OAS2, and OAS3, were increased by TRIM38 overexpression and decreased by TRIM38 knockout." (PMID 40006954, 2025). "Of note, ISG15 KO cells are still able to control DV and ZIKV infection when previously stimulated with IFNα." (PMID 38384473, 2024). "In line with our findings, the induction of ISG15 by recombinant IFN-ε has also been observed in the ectocervical cell line Ect1, which is relevant to ZIKV infection since ISG15 is known to be one of the key ISGs that protect against ZIKV." (PMID 39460364, 2024). "Immunoblot assay with anti-IFIT1 or ISG15 antibody confirmed the upregulation of ISG expression during ZIKV infection." (PMID 39178324, 2024). "In contrast to Zika virus infection, exogenous IFNɛ strongly induced ISG15, OAS1, IFIT1, and IFI6 within 12 hours post-treatment." (PMID 39621805, 2024). "Key ISGs that protect against ZIKV infection (Viperin, ISG15, IFITM1, IFI6) were significantly upregulated compared to control in all three treatments." (PMID 36897927, 2023). "Silencing of ISG15 enhanced ZIKV infectivity, while supplementation with recombinant ISG15 inhibited ZIKV infection of primary human corneal epithelial cells." (PMID 35522620, 2022). "Our study also found that in CHME3 cells ZIKV infection resulted in upregulation of type I interferon (IFNβ), interferon-stimulated genes (MX-1 and ISG15), pattern recognition receptors (RIG-I and MDA5) and IRF7." (PMID 32373079, 2020). "Two complimentary studies have demonstrated that Interferon Stimulated Gene 15 (ISG15) protects against ZIKV infection." (PMID 32937990, 2020). "The observed increase in ISG15 due to ZIKV infection at 48 hpi in U251 cells is consistent with the findings on ISG15 expression modulation due to other flaviviruses like Dengue virus (DENV) and West Nile Virus (WNV)." (PMID 30984137, 2019). "However, ISG15 has also recently been reported to be involved in promoting ZIKV infection by regulating JAK/STAT and ISGylation (the term that stands for protein conjugation with ISG15) pathways." (PMID 33810028, 2021). "These antiviral IFN-triggered ISGs exert diverse and different antiviral functions, such as inhibition of viral entry and viral protein synthesis, clearance of both viral protein and genome and inhibition of viral replication and release, as reported for ISG15 that limits ZIKV infection." (PMID 33810028, 2021). "In addition, the antiviral responses failed during ZIKV infection in ISG15-/- mice, with lower expression of RIG-I and IFN alpha-inducible protein 6 (IFI6) related ISGs and increased severity of retinal lesions." (PMID 33810028, 2021). "Hence, we examined the ISGs transcript levels for DDX58, IFIT1, ISG15, and IFNB1, and analyzed the transcript levels of inflammatory cytokines including TNF-α and IL-6 that are associated with severe symptoms during ZIKV infection." (PMID 34745057, 2021). "A follow-up study by the same group extended these observations to show that ZIKV infection in human primary corneal epithelial cells (HCEC) induced expression of ISG15 RNA and protein, and that siRNA mediated knockdown of this expression lead to increased ZIKV infection in these cells." (PMID 32937990, 2020). "Likewise, ZIKV infection of Vero cells showed a striking reduction in ISG15 and OAS1 gene expression triggered by exogenous addition of IFN." (PMID 31652496, 2019). "Increased mRNA expression levels of ISG15 upon Snx6 and/or Snx9 knockdown during ZIKV infection were observed, suggesting that disruption of MDV formation during ZIKV infection affects the host antiviral response in JEG-3 cells." (PMID 37781396, 2023).
ZIKV infection (continued). "Upon ZIKV infection, the expressions of IFN-related genes (such as IFNL1 and IFNL3) and ISG-related genes (such as ISG15 and ISG20) were only marginally elevated until 24 h.p.i." (PMID 36209057, 2022). "The overexpression of ISG15 also promoted Zika virus infection, not by increasing virus replication directly, but by downregulating the JAK/STAT signaling pathway and reduced the production of ISGs." (PMID 37637123, 2023). "The knockout of ISG15 protected iPSC-derived cerebral organoids from ZIKV infection in contrast to control cerebral organoids, consistent with a critical role for the interferon pathway in ZIKV infection." (PMID 34713254, 2021). "These included MX1, IFIT1, ISG15, SAMHD1, IFIT3, and STAT1, all of which have been shown to be similarly upregulated by ZIKV infection in other human cell types, including fibroblasts and pluripotent stem cell (iPSC)-derived neural progenitor cells (NPC), as also demonstrated by LC-MS/MS analysis." (PMID 34079533, 2021). "This study noted the induction of ATF3, EGR1, JUNB, IRF7, ISG15, HERC5/6, additional ISGs, chemokines CCL5 and CXCL10, prosurvival responses, and decreased proapoptotic genes, similar to gene induction levels we found to be induced by ZIKV infection of hBMECs (GEO GSE98889)." (PMID 28698279, 2017). "During ZIKV infection we observed a reduction of IFNL1, IFIT1, and IFIT2, but not IFNB, IFIT3, and ISG15 transcription in the absence of DNA-PKcs." (PMID 36311766, 2022). "Similarly, in RPE cells, where ZIKV infection does not induce IFNL1 transcription, the absence of DNA-PKcs decreased IFNB and IFIT2, but not ISG15 transcription." (PMID 36311766, 2022).
hepatocellular carcinoma (24 papers, 2014 to 2026). A malignant tumor that arises from hepatocytes. "miR-370 associates with the 3’UTR in Isg15 mRNA, downregulating ISG15 expression in hepatocellular carcinoma cells." (PMID 36319753, 2022). "ISG15 expression was also associated with differentiation grade and metastasis in Hepatocellular carcinoma and had prognostic value in esophageal squamous cell carcinoma patients, particularly those who consume alcohol." (PMID 28186990, 2017). "Similarly, novel HLA-A*02:01-associated TAAs specific for hepatocellular carcinoma (HCC) (i.e. ISG15) with a high sequence homology to viral-derived antigens have been predicted (i.e. Calicivirus)." (PMID 38947322, 2024). "This analysis revealed that the ISG15 mRNA level was significantly higher in all tumor tissues except for hepatocellular carcinoma tissues than in the corresponding adjacent normal tissues (upper)." (PMID 38443596, 2024). "A previous study similarly showed that ISG15 expression levels in hepatocellular carcinoma tissues were significantly correlated with tumour volume, advanced stage, and cellular differentiation." (PMID 38939897, 2024). "To this end, we compared the expression of twelve genes either linked to the induction of innate immunity (STAT1, STAT2, PKR) or IFN effector genes (OAS1/2, IFIT1–3, RSAD2, MX1, TRIM14, ISG15) in HCV-infected hepatoma cells and mature iHLCs." (PMID 29497123, 2018). "Hepatocellular carcinoma (HCC) cells under high‐fat environment constrain harmful reactive oxygen species (ROS) by enhancing glutathione synthesis though upregulating interferon stimulated gene 15 (ISG15)." (PMID 40126377, 2025). "ISG15 can also be secreted from activated cells as free ISG15 and has been shown to play putative roles in other solid tumors, such as pancreatic ductal adenocarcinoma, hepatocellular carcinoma, and nasopharyngeal carcinoma." (PMID 38644421, 2024). "ISG15 is highly expressed in hepatocellular carcinoma (HCC) tumor specimens and triggers tumorigenesis and metastasis of HCC." (PMID 27888627, 2016). "To confirm the biological IFN activity of each sample, we stimulated the human hepatocellular carcinoma cell line, HepG2, with PASC patient serum and investigated the mRNA expression level of IFN-stimulated genes (ISGs) involving Mx1, ISG15, PKR, and IFIT1." (PMID 39921694, 2025). "ISG15 and enzymes involved in ISGylation are upregulated in hepatocellular carcinoma (HCC)." (PMID 36319753, 2022). "To this end, we co-expressed UBL proteins (i.e., MYC-DDK-tagged SUMO-1, HA-tagged SUMO-2, HA-tagged SUMO-3, and MYC-DDK-tagged ISG15) with tagged HBc (i.e., FLAG-tagged or HA-tagged, depending on the used UBL protein) in Huh7 hepatocellular carcinoma cells." (PMID 33256078, 2020). "In hepatoma cells, IFNL4 gene transfection or recombinant IFN-λ4 protein treatment robustly increased the protein levels of ISG15 and USP18 in an IFNLR1-dependent manner and potently blocked IFN-α signalling." (PMID 28630501, 2017). "For example, miR-370 downregulates ISG15 expression by targeting its 3’UTR, thereby enhancing the anti-tumor activity of IFN-I in hepatocellular carcinoma (HCC) cells." (PMID 41193953, 2025). "Interestingly, in hepatocellular carcinoma (HCC) the nuclear factor erythroid 2-like 3 (NFE2L3), which has been largely involved in cancer development, induces the expression of ISG15 by binding to the antioxidant response element (ARE) located in the ISG15 promoter." (PMID 38400136, 2024).
pancreatic cancer (24 papers, 2016 to 2025). "In pancreatic cancer, ISG15 was secreted by tumour associated macrophages and promoted cancer stem cell renewal and invasiveness." (PMID 28186990, 2017). "In Pancreatic cancer stem cells (PaCSC), ISG15 and ISGylation are required for mitophagy and metabolic plasticity, loss of ISG15 lead to increased accumulation of dysfunctional mitochondria, reduced OXPHOS and impaired mitophagy and finally negatively impacts PaCSC stemness." (PMID 36778129, 2023). "ISG15 upregulation is associated with gemcitabine resistance in pancreatic cancer cells." (PMID 36319753, 2022). "FDA drug library screening revealed enhanced statin sensitivity in pancreatic cancer (PC) cells upon ISG15 knockdown." (PMID 41366470, 2025). "To dissect the metabolic consequences of ISG15 knockdown, we performed sterolomics profiling in pancreatic cancer (PC) cells." (PMID 41366470, 2025). "In pancreatic cancer, TRMT112 and WBSCR22 synergistically inhibit pancreatic cancer progression by repressing ISG15 transcription, which seems to support the possibility that TRMT112 is a tumor suppressor." (PMID 39019857, 2024). "As we showed here that necroptotic cells originated from colorectal, pancreatic cancer and histiocytic lymphoma were incapable of producing ISG15 and inducing invasiveness in HNSCC cells." (PMID 38926796, 2024). "Inhibition of ISG15/ISGylation impaired the self-renewal and tumorigenic potential of pancreatic cancer stem cells." (PMID 35159348, 2022). "Increased expression of ISG15 and its conjugation in pancreatic cancer stem cells (PaCSCs) is essential for maintaining the metabolic plasticity of PaCSCs170." (PMID 36319753, 2022). "More specifically, both paracrine secretion from M2 macrophages and autocrine ISG15 secretion from pancreatic tumour cells are able to induce a CSC phenotype in said cells." (PMID 35864381, 2022). "Using the CRISPR/Cas9 tool, they generated ISG15 and UbcH8 (a conjugate enzyme for ISG15 protein) knockdown in Panc02 murine pancreatic cancer cells." (PMID 34781949, 2021). "They found that upregulated gemcitabine resistance in cultured pancreatic cancer cells, and that the siRNA-mediated knockdown of ISG15 expression restored gemcitabine sensitivity." (PMID 27626310, 2016). "Tissue microarray analysis revealed that although both ISG15 and HMGCR were highly expressed in pancreatic cancer, their expression displayed a mutually exclusive pattern: tumor cells with elevated ISG15 exhibit low HMGCR levels, and conversely, HMGCR-high cells show minimal ISG15 expression." (PMID 41366470, 2025). "ISG15 has been identified as a critical microenvironmental factor for pancreatic cancer stem cells." (PMID 35159348, 2022). "ISG15 was shown to drive tumorigenesis and metabolic plasticity of pancreatic cancer, suggesting that its inhibition may be a treatment option for pancreatic cancer." (PMID 36077244, 2022). "Besides, ISG15 has been described to play a pro-tumoral role in various malignancies like bladder, nasopharyngeal, breast, hepatocellular or pancreatic cancer." (PMID 35864381, 2022). "The expression of ISG15 is significantly upregulated in pancreatic cancer tissues." (PMID 33051403, 2020). "Future studies should investigate whether the contribution of ISG15 to the development and maintenance of CSCs is involved in chemotherapy resistance in pancreatic cancer." (PMID 27626310, 2016). "Similarly, a previous report showed that vesicular protein could detect early pancreatic cancer, and ISG15 expression was increased in hepatic cancer, suggesting that it may serve as a potential prognostic marker in tumour biomarker for drug sensitivity." (PMID 38939897, 2024).
pancreatic cancer (continued). "Building on our prior discovery of ISG15’s role in pancreatic cancer stem cell (CSC) generation, we identified co-upregulation of ISG15 and HMGCR in pancreatic ductal adenocarcinoma (PDAC)." (PMID 41366470, 2025). "Given the synthetic lethality potential of the ISG15-HMGCR axis, we first assessed their clinical relevance in pancreatic cancer (PC)." (PMID 41366470, 2025). "In pancreatic cancer (PAAD), the WBSCR22/TRMT112 complex downregulates the oncogene ISG15 expression, impairing malignant phenotypes." (PMID 37396662, 2023).
HIV-1 infection (22 papers, 2011 to 2025). The type species of lentivirus and the etiologic agent of acquired immunodeficiency syndrome (AIDS). "Single-cycle HIV-1 infection was reduced by more than 100-fold in IFN-I-primed ISG15-deficient cells compared to unprimed ISG15-deficient cells, while only a modest 2.8-fold difference was observed in WT IFN-primed cells compared to WT unprimed cells." (PMID 35333911, 2022). "Complementation of ISG15-deficient cell lines with WT ISG15 yields IFN-I-primed cells that are more susceptible to HIV-1 infection compared to RFP-complemented ISG15-deficient cells." (PMID 35333911, 2022). "Taken together, the loss of ISG15 expression restricted HIV-1 infection, not only in hTERT-immortalized fibroblasts, but also in primary human CD4+ T cells, the main target cell population of HIV-1." (PMID 35333911, 2022). "We found ISG15 deficiency limits HIV-1 infection not only in fibroblasts, but also in human primary CD4+ T cells." (PMID 35333911, 2022). "Together, these results suggest that there is likely a set of ISGs in ISG15-deficient CD4+ T cells that is sufficient to reduce the susceptibility of primary CD4+ T cells to HIV-1 infection." (PMID 35333911, 2022). "We observed here that ISG15-deficient patient fibroblasts were more resistant to HIV-1 infection than WT cells." (PMID 35333911, 2022). "We demonstrate that IFN-I priming of ISG15-deficient cells leads to superior resistance to human immunodeficiency virus 1 (HIV-1) infection compared to IFN-I primed healthy control cells." (PMID 35333911, 2022). "In addition, while early studies indicated ISG15 deficiency inhibits HIV-1 infection, subsequent mechanistic analyses revealed that this is due to free cellular ISG15 aids the stabilization of the ubiquitin-specific peptidase 18 (USP18), a negative regulator of type I interferon (IFN-I) signaling." (PMID 40568704, 2025). "Studies have shown that although HIV-1 infection upregulates ISG15, the virus circumvents ISG15’s antiviral effects by inhibiting ISGylation." (PMID 40284971, 2025). "Together these findings indicate that the proviral role of ISG15 in HIV-1 infection is an ISGylation independent process." (PMID 35333911, 2022). "In order to determine the role of ISG15 in HIV-1 infection in primary CD4+ T cells, we infected the ISG15KO CD4+ T cells with HIV-1." (PMID 35333911, 2022). "Transcriptional profiling data revealed that HERC5 and ISG15 RNA expression are significantly increased in lymphatic tissue during acute HIV-1 infection in patients with asymptomatic and acute stages of AIDS and patients with AIDS." (PMID 22093708, 2011). "Furthermore, sustained upregulation of this ISG cluster, including ISG15, MX1, OAS1 and STAT1, is a hallmark of untreated HIV-1 infection." (PMID 41226717, 2025). "ISG15 represents another negative regulator of HIV-1 infection that modulates STING activation." (PMID 41373786, 2025). "IFN-I signaling and the role of ISG15 in the context of HIV-1 infection is poorly understood." (PMID 35333911, 2022). "Overexpression of Vpr resulted in increased ISG15 mRNA expression, which was in agreement with previous studies showing that Vpr is involved in the majority of changes in gene expression after HIV-1 infection." (PMID 36458014, 2022). "Taken as a whole, the downregulation of ISG15 could result in a weakened protective response against HIV-1 infection." (PMID 33080839, 2020). "We found that ISG15 could serve as a reliable biomarker for HIV-1 infection in several independent datasets." (PMID 28771541, 2017). "During HIV-1 infection, ISG15 promotes the ISGylation of STING—a covalent attachment of ISG15 to the target protein—that facilitates STING oligomerization and enhances cGAS-STING pathway activation." (PMID 41373786, 2025). "We found that HIV-1 infection induced the expression of a set of ISGs (RSAD2, ISG15, IFI44L, and IFI27) that remained upregulated during the chronic phase of HIV-1 infection." (PMID 39104769, 2024).